MTFP1 (mitochondrial fission process 1)
Description:
Plays a role in the regulation of mitochondrial morphology. Inhibits mitochondrial fusion by creating a non-fusogenic lipid environment which affects OPA1 oligomerization and its subsequent capacity to drive fusion. This prevents defective inner mitochondrial membrane (IMM) subdomains from fusing with other mitochondria, facilitating their segregation into small MTFP1-enriched mitochondria (SMEM) which are targeted for autophagic degradation. This IMM quality control mechanism controls mitochondrial DNA levels.
Synonyms: MTP18; HSPC242
Tractability: Antibody: UniProt predicts a signal peptide or a membrane-spanning region. PROTAC: ubiquitination databases record sites on it; its protein half-life has been measured.
Gene: Protein-coding gene on chromosome 22 (30,425,623 to 30,429,054, forward strand). Ensembl gene ENSG00000242114.
Subcellular location: Mitochondrion inner membrane
Subcellular location (Human Protein Atlas): Mitochondria
Gene Ontology:
Molecular function: protein binding
Biological process: mitochondrial fission; negative regulation of mitochondrial fusion
Cellular component: mitochondrial inner membrane; mitochondrion
Genetic constraint (gnomAD): Loss-of-function variants: 19 observed, 17 expected, observed/expected ratio (o/e) 1.12, 90% interval 0.78 to 1.63. The upper end of that interval is the gene's LOEUF score, 1.63, which puts it in group 6 of 6, group 1 being the genes least tolerant of losing a copy. Missense variants: 221 observed, 230.89 expected, observed/expected ratio (o/e) 0.96, 90% interval 0.86 to 1.07. Synonymous variants: 89 observed, 98.47 expected, observed/expected ratio (o/e) 0.9, 90% interval 0.76 to 1.08.
Homologues: Orthologues: chimpanzee MTFP1 (100% identical), rabbit MTFP1 (93% identical), guinea pig MTFP1 (90% identical), mouse Mtfp1 (87% identical), rat Mtfp1 (84% identical), dog MTFP1 (84% identical), tropical clawed frog mtfp1 (67% identical), pig MTFP1 (63% identical), zebrafish MTFP1 (53% identical), Caenorhabditis elegans mtp-18 (49% identical), Drosophila melanogaster CG7772 (43% identical).
Diseases named in the same sentence as MTFP1 in open-access papers:
MTFP1 is named in the same sentence as 53 diseases in open-access papers, as found by Europe PMC text mining. Sharing a sentence is not in itself a finding about the gene and the disease. The quoted sentences say what the papers report.
hepatocellular carcinoma (7 papers, 2018 to 2025). A malignant tumor that arises from hepatocytes. "Studies in hepatocellular carcinoma (HCC) have shown that MTFP1 regulates immune cell function in the tumor microenvironment by affecting calcium homeostasis and mitochondrial division of liver tumor cells." (PMID 41030636, 2025). "Recently, MTFP1 has also been implicated in promoting the migratory ability of adipose-derived stem cells as well as MMP9 expression and cancer metastasis in hepatocellular carcinoma although the underlying mechanisms are still unknown." (PMID 35589683, 2022).
oral cancer (4 papers, 2023 to 2025). "Moreover, MTFP1-mediated mitophagy provide a survival benefit to oral cancer cells, and MTFP1 deficiency triggers apoptosis, suggesting MTFP1 controls cell survival through mitochondrial fission and/or mitophagy in oral cancer cells." (PMID 40395309, 2023). "To understand the connection between MTFP1-induced mitochondrial fission and mitophagy in oral cancer cells, we studied mitophagy in DNM1L deficient cells expressing MTFP1 and found that MTFP1 controls mitochondrial fission during CCCP (carbonyl cyanide m-chlorophenylhydrazone)-induced mitophagy." (PMID 40395309, 2023). "Consistent with this, a recent study also identified IMM protein MTFP1 (MTP18) as a mitophagy receptor that interacts with LC3-II in response to carbonyl cyanide m-chlorophenyl hydrazone (CCCP)-induced OMM rupture in oral cancer cells." (PMID 41194217, 2025). "Thus, targeting MTFP1-associated mitophagy could represent a strategy for oral cancer therapy." (PMID 40395309, 2023). "We also observed that MTFP1 is beneficial to oral cancer cell survival exposed to anticancer drugs, such as cisplatin, through mitophagy, since inhibition of MTFP1-dependent mitophagy induced cell death." (PMID 40395309, 2023). "Moreover, knockdown of PRKN (parkin RBR E3 ubiquitin protein ligase) or PINK1 (PTEN-induced kinase 1) abolished mitophagy in MTFP1-overexpressing oral cancer cells." (PMID 40395309, 2023). "Interestingly, mutation of MTFP1 LIR motif (MTFP1mLIR) inhibits this interaction, decreasing mitophagy in oral cancer cells." (PMID 40395309, 2023). "Thus, we examined cell death programs in MTFP1-overexpressing oral cancer cells treated with cisplatin in the presence of wortmannin, a PI3K inhibitor, and Mdivi1, a DNM1L inhibitor that also blocks MTFP1-induced mitophagy." (PMID 40395309, 2023). "Finally, we explored whether MTFP1 is beneficial for the survival of oral cancer cells exposed to anticancer drugs such as cisplatin." (PMID 40395309, 2023). "Furthermore, MTFP1-depleted cells showed elongated mitochondria that form a more extensive mitochondrial network than in control cells, confirming that MTFP1 controls mitochondrial fission in oral cancer cells." (PMID 40395309, 2023). "Thus, targeting MTFP1 could be a potential therapeutic strategy for treating oral cancer and possibly other malignancies." (PMID 40395309, 2023).
gastric cancer (3 papers, 2017 to 2022). A primary or metastatic malignant neoplasm involving the stomach. "Why other groups have reported that MTFP1 depletion can protect gastric cancer and cardiomyocyte cell lines from PCD induced by various cell death triggers including doxorubicin is unclear." (PMID 36333300, 2022).
neuroblastoma (3 papers, 2016 to 2024). Neuroblastoma (NB) is the most common solid, extracranial childhood tumor. "The same applies to MTFP1, a key player in mitochondria dynamics, which is induced by hypoxia in neuroblastoma cells and contains putative HIF-response elements in its promoter." (PMID 39078527, 2024).
prostate carcinoma (3 papers, 2017 to 2025). A carcinoma that arises from epithelial cells of the prostate gland. "In prostate cancer, MTFP1 affects the proliferative ability of cancer cells by regulating cell cycle-related signaling pathways." (PMID 41030636, 2025). "In prostate cancer, MTFP1 affects calcium ion transmission and metabolic signaling by regulating the formation of MAMs." (PMID 41030636, 2025). "A novel Mitochondrial Protein 18 (MTP18), also known as Mitochondrial Fission Protein 1 (MTFP1), was first demonstrated to implicate in the regulation of mitochondrial fission in human prostate cancer (PC-3) cells and human keratinocytes (HeCaT)." (PMID 28915614, 2017). "In addition, MTFP1 promotes aggressiveness and treatment tolerance in prostate cancer by regulating lipid metabolism." (PMID 41030636, 2025).
atherosclerosis (2 papers, 2021 to 2025). A disease characterized by the build-up of fatty material and calcium deposition in the arterial wall resulting in partial or complete occlusion of the arterial lumen. "In 46 upregulated OCRGs in MDs, upregulation of two regulators VAMP8 and SERPINA1 was shared between obese and atherosclerosis; and two upregulated regulators DNM2 and MTFP1 were shared between T2D and atherosclerosis." (PMID 34368262, 2021).
breast carcinoma (2 papers, 2025). "For example, in HER2-positive breast cancer, low expression of MTFP1 is associated with resistance to chemotherapeutic drugs; In non-small cell lung cancer, the dysfunction of MTFP1 leads to the cancer cells' resistance to radiotherapy." (PMID 41030636, 2025). "In breast cancer, the abnormally high expression of MTFP1 promotes excessive mitochondrial division, weakens mitochondrial OXPHOS function, and promotes the transition of cancer cells to glycolytic metabolism." (PMID 41030636, 2025). "Drug development targeting the pathway related to MTFP1 and mitochondrial dynamics is expected to significantly improve the therapeutic effect in breast cancer patients." (PMID 41030636, 2025). "In breast cancer, MTFP1 maintains the balance between apoptosis and autophagy by regulating mitochondrial structure." (PMID 41030636, 2025). "Studies have shown that the aberrant expression of MTFP1 in HER2-positive breast cancer is closely related to aggressiveness, which may affect the therapeutic sensitivity of cancer cells by regulating metabolic reprogramming." (PMID 41030636, 2025).
cardiomyopathy (2 papers, 2022). A disease of the heart muscle or myocardium proper. "MTFP1 is a potential pro-apoptotic protein, and a recent study demonstrated that knockdown of MTFP1 could improve doxorubicin-induced cardiomyopathy." (PMID 35475469, 2022). "A recent study showed that knockdown of MTFP1 could improve doxorubicin-induced cardiomyopathy, suggesting that MTFP1 may be involved in the cardiovascular disease." (PMID 35475469, 2022). "In line with the notion that increased proton leak is maladaptive for the heart, our study shows that MTFP1 loss in cardiomyocytes reduces the mitochondrial membrane potential as a result of increased proton leak through the IMM preceding the onset of cardiomyopathy." (PMID 36333300, 2022). "Together, these data indicate that Mtfp1 deletion does not impinge upon cardiomyocyte excitation-contraction coupling before the onset of cardiomyopathy in vivo." (PMID 36333300, 2022).
dilated cardiomyopathy (2 papers, 2022 to 2025). Cardiomyopathy which is characterized by dilation and contractile dysfunction of the left and right ventricles. "Constitutive knockout of cardiomyocyte MTFP1 in mice resulted in a fatal, adult-onset dilated cardiomyopathy accompanied by extensive mitochondrial and cardiac remodeling during the transition to heart failure." (PMID 36333300, 2022). "Our in vivo studies revealed that cardiomyocyte-specific deletion of MTFP1 (cMKO) drives the progressive development of dilated cardiomyopathy (DCM) beginning at 18 weeks of age culminating in chronic heart failure and middle-aged death in both male and female mice." (PMID 36333300, 2022).
heart failure (2 papers, 2022 to 2024). Inability of the heart to pump blood at an adequate rate to meet tissue metabolic requirements. "Inhibition of mitochondrial fission process 1 has been shown to decrease the progression of heart failure by preserving mitochondrial membrane integrity." (PMID 38169612, 2024). "Taken together, our data reveal an unappreciated and critical role of MTFP1 in bioenergetic efficiency and mitochondrial uncoupling, particularly evident in metabolically active cardiomyocytes, which precedes the manifestation of cardiac dysfunction and heart failure in cMKO mice." (PMID 36333300, 2022). "Thus, our work now positions MTFP1 as a critical regulator of mitochondrial coupling through ANT in cardiomyocytes and its loss leads to membrane potential dissipation associated to mPTP opening, cell death and progressive DCM that leads to heart failure, and middle-aged death in mice." (PMID 36333300, 2022).
ischaemia (2 papers, 2023 to 2025). "When cardiomyocytes face stress such as ischemia-reperfusion injury, the dysfunction of MTFP1 often exacerbates the damage of cells." (PMID 41030636, 2025). "MTFP1 plays a key protective role by maintaining mitochondrial functional integrity in a variety of muscle pathological states, especially in the presence of ischemia-reperfusion injury or metabolic disorders." (PMID 41030636, 2025).
Anxiety (1 paper, 2022). Intense feelings of nervousness, tension, or panic often arise in response to interpersonal stresses. "In conclusion, the homologous mutation in the Timm8a1 gene caused the hearing impairment, memory impairment, and anxiety-like behavior, and the latter two phenotypes may be correlated with reduced mitochondrial size regulated by upregulation levels of mitochondrial fission factor, MTFP1." (PMID 36090790, 2022).
cervical cancer (1 paper, 2017). A primary or metastatic malignant neoplasm involving the cervix. "In contrast, in the human cervical cancer cell lines, Mtfp1 is responsible for mitochondrial fission, and knockdown of Mtfp1 results in mitochondrial fusion." (PMID 28643438, 2017).
colorectal cancer (1 paper, 2025). A primary or metastatic malignant neoplasm that affects the colon or rectum. "Dysregulation of MTFP1 in colorectal cancer cells is strongly associated with mitochondrial fragmentation, leading to preferential use of glycolytic pathways." (PMID 41030636, 2025). "In colorectal cancer, MTFP1 plays a key role in tumor progression by regulating mitochondrial morphology and maintaining cellular oxidative phosphorylation." (PMID 41030636, 2025). "Aberrant expression of MTFP1 in colorectal cancer can serve as a potential prognostic marker." (PMID 41030636, 2025).
Hepatic steatosis (1 paper, 2023). Steatosis is a term used to denote lipid accumulation within hepatocytes. "Here the authors show that ablation of Mitochondrial Fission Process 1 in hepatocytes in mice protects fatty liver disease and dysfunction caused by high fat diet." (PMID 38123539, 2023). "This pro-survival role of MTFP1 in the liver appears to be independent from the metabolic protection its deletion confers against HFD-induced hepatic steatosis, since HFD-feeding does not cause cell death." (PMID 38123539, 2023). "Hence, the mitochondrial mechanisms through which MTFP1 ablation protects against hepatic steatosis appears to be functionally distinct from pathways currently being pursued as therapeutic interventions for MASLD and associated pathologies." (PMID 38123539, 2023). "We report that deletion of Mtfp1 in vivo in hepatocytes enhances hepatic OXPHOS activity and confers protection against diet-induced liver steatosis, weight gain and systemic glucose dysregulation when mice are fed a high fat diet (HFD)." (PMID 38123539, 2023). "Altogether, our data demonstrate that Mtfp1 deletion in hepatocytes confers metabolic resistance to hepatic steatosis in vivo in a manner that is independent of apoptotic resistance." (PMID 38123539, 2023).
melanoma (1 paper, 2021). A malignant, usually aggressive tumor composed of atypical, neoplastic melanocytes. "Mammalian target of rapamycin complex 1 (mTORC1), which is a trigger factor in cancers, stimulates translation of mitochondrial fission process 1 (MTFP1), which is coupled to pro-fission phosphorylation and mitochondrial recruitment of DRP1 in melanoma cells." (PMID 33498743, 2021).
non-small cell lung carcinoma (1 paper, 2025). A group of at least three distinct histological types of lung cancer, including non-small cell squamous cell carcinoma, adenocarcinoma, and large cell carcinoma. "In small cell lung cancer and non-small cell lung cancer (NSCLC), MTFP1 regulates the imbalance between mitochondrial fusion and division and promotes glycolytic metabolism of tumor cells." (PMID 41030636, 2025).
Obesity (1 paper, 2025). Accumulation of substantial excess body fat. "Decreased expression of MTFP1 was linked to increased expression of PPARG (Peroxisome Proliferator-Activated Receptor Gamma) and LPL (Lipoprotein Lipase), two known obesity-related genes important for adipogenesis, lipid metabolism, and ultimately energy homeostasis." (PMID 40216759, 2025).
oral squamous cell carcinoma (1 paper, 2025). "MTFP1 is involved in developing and occurring oral squamous cell carcinoma; its overexpression-mediated mitochondrial fragmentation and subsequent ROS production promote cancer growth." (PMID 40725242, 2025).
Sepsis (1 paper, 2023). Sepsis is defined as life-threatening organ dysfunction caused by a dysregulated host response to infection. "MTFP1 was the most significantly down-regulated mRNA in the aortic tissue of rats with LPS-induced sepsis." (PMID 36611198, 2023). "We observed significant down-regulation of MTFP1 in the aortic tissues of rats with LPS-induced sepsis." (PMID 36611198, 2023).
steatosis (1 paper, 2023). Increased lipid within the cytoplasm of cells. "To determine whether hepatocyte deletion of Mtfp1 prevents steatosis in a cell-autonomous manner, we established an assay in which we could mimic HFD-induced steatosis in primary hepatocytes isolated from NCD-fed mice." (PMID 38123539, 2023).
cancer (14 papers, 2017 to 2025). A tumor composed of atypical neoplastic, often pleomorphic cells that invade other tissues. "In the context of cancer, MTFP1 expression may be closely linked to tumor invasiveness and drug resistance, thereby offering new insights into the potential of cancer therapies targeting MTFP1." (PMID 41030636, 2025). "The abnormal function of MTFP1 not only changes the proliferation and invasion ability of tumor cells, but also affects the polarization and function of tumor-associated immune cells, thereby enhancing the immune escape ability of cancer cells." (PMID 41030636, 2025). "Drug development targeting MTFP1, especially by inhibiting MTFP1-induced mitochondrial fragmentation, can impair the metabolic adaptability of cancer cells and increase their sensitivity to conventional chemotherapy and radiotherapy." (PMID 41030636, 2025). "The clinical application of MTFP1 as a drug target is promising and covers a variety of complex diseases such as metabolic diseases and cancer." (PMID 41030636, 2025). "For example, studies have shown that inhibiting MTFP1 function can trigger mitochondrial fragmentation in cancer cells, reducing their ability to adapt to energy metabolism and thereby increasing the effects of chemotherapy and radiation therapy." (PMID 41030636, 2025). "Mounting evidence implicates MTFP1 dysfunction in the pathogenesis of diverse diseases including cardiovascular disorders, myopathies, and cancer." (PMID 41030636, 2025). "MTFP1 is considered a potential target in cancer therapy due to its critical role in a variety of cancers." (PMID 41030636, 2025). "MTFP1 regulates the metabolic flexibility and antiapoptotic capacity of cancer cells by affecting the balance of mitochondrial fusion and division." (PMID 41030636, 2025). "Metabolic reprogramming of cancer cells is a core feature of tumor growth and survival, and the regulatory role of MTFP1 in this process is crucial." (PMID 41030636, 2025). "By simultaneously regulating the mitochondrial division and fusion pathways, combined therapy targeting MTFP1 and related proteins can effectively inhibit the metabolic reprogramming of cancer cells and increase the efficacy of chemotherapy or radiotherapy." (PMID 41030636, 2025). "Future research should focus on developing highly specific MTFP1 inhibitors or activators in combination with other treatments such as immunotherapy to achieve more effective and safer cancer treatments." (PMID 41030636, 2025). "MTFP1 affects metabolic pathways, apoptosis signaling, and cell cycle regulation in cancer cells by regulating mitochondrial fusion." (PMID 41030636, 2025). "The research on targeted precision therapy for the mechanism of MTFP1 in cancer provides a new perspective for understanding the complexity of tumor biology and developing more effective cancer treatment strategies." (PMID 41030636, 2025). "The complex role of MTFP1 in tumor heterogeneity has been extensively studied in multiple cancers such as breast, lung, and prostate." (PMID 41030636, 2025). "The reduced expression of the miR-125b-5p and overexpression of MTFP1 (mitochondrial fission process 1) in cancer have been shown, so it can be concluded that miR-125b-5p acts as a suppressor and MTFP1 as an oncogene." (PMID 37371799, 2023). "The dysregulation of MTFP1 in cancer cells is often manifested by increased mitochondrial fragmentation, a phenomenon that is not only related to the Warburg effect (cancer cells favor the glycolytic pathway under aerobic conditions), but also enhances the cell’s resistance to apoptosis." (PMID 41030636, 2025).